IL6 (interleukin 6)
Diseases named in the same sentence as IL6 in open-access papers (continued):
Sharing a sentence is not in itself a finding about the gene and the disease.
Cachexia (continued). "Furthermore, IL-6 trans-signaling/STAT3 axis was identified as a therapeutic target in advanced cancer patients presenting cachexia." (PMID 31114509, 2019). "In addition, immune cells in the microenvironment such as M1/M2 macrophage, CD8+ T lymphocyte, NK cells, etc. can affect the tumor growth, progression, and cachexia of HNSCC by secreting IL-6." (PMID 31620361, 2019). "This is consistent with previous study that exogenous IL6 can induce cachexia and muscle wasting." (PMID 31293430, 2019). "Physiological conditions of sustained high IL-6 in circulation in humans include cachexia." (PMID 31652937, 2019). "In the context of cachexia, IL-6 is a well-studied cytokine." (PMID 31769424, 2019). "Known factors involved in cachexia, IL-1α, IL-1β, IL-6, IL-8 and TNFα are all proteins that may be produced by the innate immune cells or other non-immune cell types such as epithelial cells or stromal cells." (PMID 30513792, 2018). "The difficulty in alleviating cachexia by using monotherapies against pro-inflammatory humoral factors such as TNFα and IL-6 has been attributed to the redundancy of downstream effectors of these cytokines and the presence of multiple signaling pathways sufficient to induce atrophy." (PMID 29849089, 2018). "Interestingly, previous results from our group have demonstrated that subcutaneous adipose tissue is an important source of IL-6 in cancer patients with cachexia." (PMID 30094378, 2018). "In vivo evidence of the specific involvement of IL6/STAT3 in causing cachexia-associated muscle wasting is that ApcMin/+ mice lacking IL6 do not develop cachexia." (PMID 30072615, 2018). "But how does IL-6 bind to cachexia and what therapeutic role can it have?" (PMID 30426026, 2018). "Indeed, IL-6 concentrations were proportional to the severity of cachexia and the removal of primary tumor was followed by a significant reduction in IL-6 levels." (PMID 30294279, 2018). "Consistently, the onset of cachexia symptoms was prevented with anti-IL-6 monoclonal antibodies." (PMID 30294279, 2018). "Moreover, systemic overexpression of IL6 in cancer-free mice or pre-cachectic ApcMin/+ mice accelerates the onset of cachexia." (PMID 30072615, 2018). "But between the results obtained on murine cachexia models in different types of cancers, there are differences: in IL-6 mechanisms of action and in inhibition of various IL-6-dependent signaling pathways by attenuating or eradicating the progression of cachexia." (PMID 30426026, 2018). "Data from patient studies further solidify the notion that IL-6 blockade mitigates cachexia." (PMID 30081609, 2018). "IL-6 is an important mediator in the onset of muscle wasting in numerous cachexia murine models." (PMID 29849089, 2018). "Indeed, multiple groups have found that STAT3 activation and protein levels correlates with serum IL-6 levels in cachexia murine models as well as patients." (PMID 29849089, 2018). "Together, we show that IL-6 trans-signaling is a novel autophagy-inducing pathway that may be important in cachexia development and targeted in cachectic patients." (PMID 28515477, 2017). "In order to better understand the consequence of ACVR2B/Fc administration to healthy animals and mice treated with Folfiri, we also assessed the circulating levels of IL-6 and activin A, previously reported to play a major role in promoting cachexia and in the regulation of muscle and bone mass." (PMID 29089584, 2017). "Notably, the cachexia-associated, pro-inflammatory TNF was upregulated 2.9-fold after weight loss, while expression of all interleukins (IL1B, IL6, IL10), as well as CCL3 was much lower than in the lean group." (PMID 27900559, 2017). "IL-6 trans-signaling may therefore be especially important in tissues that are severely affected during cachexia, such as lean tissue." (PMID 28515477, 2017).
Cachexia (continued). "In addition, the plasma levels of IL6 (pg/ml) were elevated in cachexia (4.10 pg/ml), whereas, detection in the control (0.00 [0.00; 0.84] pg/ml) and WSC (0.62 [0.00; 1.77] pg/ml) were low." (PMID 28288584, 2017). "While IL-6 can activate numerous cellular signaling pathways, the phosphorylation of immediate downstream target signal transducer and activator of transcription 3 (STAT3) has been most widely examined with cachexia-induced muscle mass loss." (PMID 28785374, 2017). "Several pro-inflammatory factors, such as TNFα, IL-1β and IL-6 are up-regulated by in the adipose tissue during cachexia, and we have shown before, that the subcutaneous depot presents a relevant contribution to systemic inflammation as these factors reach the circulation." (PMID 28288584, 2017). "This is in support of an important role of IL-6 in autophagy acceleration and cachexia development." (PMID 28515477, 2017). "IL-6 is recognized as a mediator of cancer-related cachexia and thus may be a driver of cachexia in MF." (PMID 27017614, 2016). "In a study of patients with advanced upper GIT cancer or NSCLC, IL-1ß was shown to be a better predictor of cachexia than IL-6, which did not correlate with weight loss in this study population." (PMID 26856534, 2016). "Furthermore, inflammation status was evaluated by analyzing levels of inflammatory cytokine IL-6 which are known to be increased in the CT-26-induced cachexia conditions." (PMID 27462398, 2016). "When taken with the more subtle effects on metabolism, and in particular the rescue of the octanoate response, these data suggest that successful reversal of cachexia may require co-administration of anti-IL-6 with nutritional support." (PMID 27829137, 2016). "In addition, high IL-6 levels correlated with cachexia phenotype, while treatment with monoclonal antibody to IL-6 reversed this picture." (PMID 26504362, 2015). "IL-6 has been recently shown to regulate glucose homeostasis in myeloid cells and induce the switch from white adipose tissue to brown fat in cancer induced cachexia." (PMID 25974216, 2015). "Based on these findings, IL-6 could have a role in host immune suppression and induction of cachexia in times of late neoplastic growth in animals with EAT." (PMID 26347589, 2015). "In this regard, the data shown in the present study confirm previous observations indicating that the levels of circulating IL-6, a pro-inflammatory cytokine that plays a pivotal role in the onset and progression of cachexia, markedly increase in tumor-bearing mice." (PMID 26636649, 2015). "Therefore in the present study we evaluated the association of these candidate polymorphisms in the AKT1, IL6, and SELP genes with cachexia in a total population of 303 PDAC patients, in two independent cohorts." (PMID 25238546, 2014). "IL-6, which is a multifunctional cytokine involved in the inflammatory and immunologic responses that are characteristic of many autoimmune diseases, is considered to be a key mediator of cachexia." (PMID 25010770, 2014). "IL-6 triggers oncogenic/angiogenic signals and the cytokine-dependent pro-cachexia cascade." (PMID 24886605, 2014). "In the blood samples, WBC counts were higher in the cachexia group (11,722 vs. 5,873/μL), as were CRP content (7.1 vs. 2.5 mg/dL), and serum IL-6 levels (40.2 vs. 13.0 pg/mL); however, the cachexia group’s albumin levels were lower (2.7 vs. 3.5 g/dL) than in the non-cachexia group." (PMID 25010770, 2014). "The C26 model of cachexia is characterized by elevated plasma levels of IL-6." (PMID 24667661, 2014). "We therefore determined whether these FBEs within the Cebpb promoter are also necessary for increased Cebpb transcription in response to IL-6, a predominant cytokine in the C26 model of cancer cachexia." (PMID 25539728, 2014).
Cachexia (continued). "Indeed, the circulating inflammatory cytokines such as TNF-α, IL-6, TGFβ family members (e.g., myostatin and activin) seem to have a role in inducing cachexia acting both peripherally on the muscle and centrally on the CNS." (PMID 24757285, 2014). "In summary, the ApcMin/+ mouse becomes hypogonadal with the progression of cachexia severity and elevated circulating IL-6 levels may have a role in the development of hypogonadism during cancer cachexia." (PMID 24285707, 2013). "In addition we have reported a marked reduction in voluntary exercise in the cachectic ApcMin/+ mouse; however, forced treadmill training during IL-6 induced cachexia in the ApcMin/+ mouse is able to increase muscle oxidative capacity and prevent weight loss." (PMID 24285707, 2013). "The development of cachexia in the ApcMin/+ mouse is dependent on the cytokine IL-6." (PMID 24285707, 2013). "We also report that exercise training can improve the expression of proteins regulating mitochondrial biogenesis and dynamics, which is associated with the attenuation of muscle protein degradation even when systemic IL-6 levels are comparable to what is typically observed during severe cachexia." (PMID 22769563, 2012). "Related to the regulation of mitochondrial fission, our data show an increase in muscle FIS1 protein expression in the later stages of cachexia, which could also be induced by systemic over-expression of IL-6." (PMID 22769563, 2012). "While our current study reports that two weeks of elevated circulating IL-6 was not sufficient to reduce muscle mitochondrial content, the IL-6r antibody treatment after the initiation of cachexia was able to significantly attenuate the loss of mitochondria." (PMID 22769563, 2012). "Furthermore, treatment with hochuekkito reduced the serum IL-6 level and inhibited IL-6 production in macrophages in tissues surrounding tumors in mice with cachexia." (PMID 23326296, 2012). "After the initiation of cachexia, we hypothesized that the suppression of IL-6 signaling would rescue muscle mass through the induction of muscle protein synthesis and repression of ATP dependent protein degradation." (PMID 21949739, 2011). "IL-6 has been connected to cachexia by both clinical and in vivo studies." (PMID 21832306, 2011). "Because of the catabolic effects that may be mediated through IL-6 during cachexia, several therapies have been proposed to inhibit IL-6 activity to prevent the progression of cachexia." (PMID 21949739, 2011). "Inhibition of IL-6 production in this cachexia model is established to prevent the development of cachexia as shown after treatment with a murine antibody to IL-6, whereas TNF-α is thought to play an important role in wasting of fat and to induce IL-6 secretion by many cell types." (PMID 19018259, 2008). "Furthermore, exercise-derived myokines such as IL-7, IL-15, and IL-6 act systemically, promoting T cell and NK cell survival while simultaneously exerting anti-inflammatory effects that may mitigate cancer-related cachexia and support immune competence." (PMID 41562839, 2026). "In addition to IL-6, IL-4 and IL-8 also play regulatory roles in the process of cachexia." (PMID 41526343, 2026). "Osteocalcin plays a key role in ensuring optimal exercise performance in mice by participating in the osteocalcin-IL-6 signaling pathway activated during physical exercise; this axis may be weakened in states of cachexia, but its functionality can be restored through training intervention." (PMID 40869331, 2025). "As a consequence, prevention of IL-6 activity by specific neutralizing antibodies or STAT3 inhibitors may represent another potential research area of new therapeutic agents to prevent lipolysis, brown adipocyte conversion, and cancer-associated cachexia." (PMID 40227577, 2025).
Cachexia (continued). "IL-6 knockout animals induced with the disease showed greater weight gain and did not develop cachexia, compared to wild animals, indicating that cachexia induced by IL-6 secretion may be a mechanism of adaptation to cancer, leading to the increased life expectancy of animals." (PMID 39861087, 2024). "Notably, IL-6 was increased in the AP on day 7 following tumor inoculation, with the levels remaining elevated till the endpoint of the experiment when the animals had developed cachexia." (PMID 38824130, 2024). "We reasoned that increased circulating IL-6 during cancer progression readily enters the AP and results in AP neuron activation – like the intravenously administered exogenous IL-6 – leading to hyperactivity in these neurons, which results in AP network hyperactivity and ultimately cachexia." (PMID 38824130, 2024). "Notably, serum levels of TNF-α and IL-6, the pro-inflammatory cytokines most commonly implicated in cancer cachexia did not correlate with the degree of weight loss or predict the occurrence of cachexia at the diagnosis of PC in this study." (PMID 37280516, 2023). "Various pro-inflammatory factors such as TNF-α and IL-6 have been implicated in cancer cachexia, but the circulating levels of those factors do not differ significantly between PC patients with and without cachexia." (PMID 37280516, 2023). "Clinical studies have established that cachexia is not a nutritional deficiency and is linked to expression of certain proteins (e.g., interleukin-6 and C-reactive protein), but much remains unknown about this often fatal syndrome." (PMID 36973755, 2023). "It is noteworthy that, similar to TNFα, targeting IL-6 alone may not be sufficient to treat or reverse skeletal muscle loss in cachexia." (PMID 36077789, 2022). "Increased plasma levels of fatty acids, TNF-α, IL-1, IL-6, glycerol, and lipid-mobilizing factors (zinc-2 glycoprotein-1) support the idea that increased triacylglycerol (TG) degradation may contribute decisively to cachexia." (PMID 35159388, 2022). "Also, other cachexigenic factors besides IL-1Ra and IL-1β may control IL-6 production and induce cachexia in this model." (PMID 33557173, 2021). "In addition, pro-inflammatory cytokines, such as TNF-α, IL-1, and IL-6, produced in the tumor micro-environment may have also affected cachexia in the group that experienced recurrence." (PMID 34362219, 2021). "Indeed, increased circulating levels of inflammatory cytokines (e.g., interleukin-6 (IL-6), tumor necrosis factor alpha (TNF-α) and C-reactive protein) and innate immune cells (e.g., neutrophils) are all associated with cachexia in humans." (PMID 34439145, 2021). "Indeed, IL-6, associated with proinflammatory immune response, activates JAK/STAT signaling and drives the secretion of glucocorticoid that causes loss of muscle, a typical characteristic of cancer cachexia." (PMID 33801569, 2021). "Cell-type expression of IL-6 might also dictate cachexia phenotypes." (PMID 33851955, 2021). "Interestingly, the negative role of IL-6 in the control of muscle mass was initially demonstrated using animal models of inflammation and cancer-associated cachexia." (PMID 31114509, 2019). "Notably, IL6 can also directly regulate the hypothalamic-pituitary-adrenal axis, and may further contribute to cachexia through its activity in the brain." (PMID 31058816, 2019). "Thus, blocking IL6 production by nonsteroidal anti-inflammatory drugs or IL6 neutralizing monoclonal antibody in a mouse model of cancer associated cachexia reduces the severity of wasting and suppresses the browning capacity of subcutaneous WAT." (PMID 30158466, 2018). "Additionally, TNF-α, IL-6, and other inflammatory factors lead to anorexia, the activation of skeletal muscle protein degradation, and the inhibition of protein synthesis; the following systemic inflammatory response aggravates cachexia." (PMID 28489606, 2017).
Cachexia (continued). "Thus, it would seem reasonable that higher systemic levels of CRP, TNF-α, IL-1ß, and IL-6 could be contributing factors to cachexia also in COPD patients." (PMID 22708547, 2012). "In this study, we used an IL-6 receptor antibody to inhibit IL-6 signaling after the initiation of cachexia, used systemic IL-6 over-expression to initiate cachexia, and also examined the effect of exercise to improve muscle mitochondrial function during IL-6 induced cachexia." (PMID 22769563, 2012). "Serum succinate levels in cachexia patients are positively correlated with CRP and IL-6 levels, indicating a predominant inflammatory effect of this molecule in CCs." (PMID 40869331, 2025). "To delineate the contribution of IL-6 family members to cachexia, we compared the GSEA results from the IL-6 pumps to those from the liver of KL mice and the liver of mice bearing allografts of the C26 cell lines, another commonly utilized cachexia model." (PMID 41278737, 2025). "We found elevated circulating levels of IL-6 and GDF15 at established cachexia, in agreement with previous studies using the C26 tumor-bearing mouse model, but also moderately increased levels of these cytokines at the pre-Cx stage." (PMID 40124481, 2025). "Intercellular signalling within the TME—mediated by cytokines such as IL-6, TGF-b, and galectins—further promotes tumour growth and systemic effects like cachexia." (PMID 41009413, 2025). "In cachexia-prone malignancies, the TME is enriched with pro-inflammatory cytokines such as IL-6, TNF-α, IL-1β, and IFN-γ, secreted by both tumor and immune cells including macrophages, MDSCs, and T cells." (PMID 40704145, 2025). "For instance, tumor-derived sEVs enriched in miR-21 have been shown to activate Toll-like receptors 7 and 8 (TLR7/8), inducing proinflammatory cytokines such as IL-6 and TNF-α, and promoting cachexia in murine cancer models." (PMID 40806377, 2025). "Particularly, IL-6 and GDF15 have been functionally involved in animal models of cancer anorexia-cachexia." (PMID 40124481, 2025). "IL-6 increases AMPK activity in C2C12 cells and murine cachexia models, contributing to catabolic signaling." (PMID 40704145, 2025). "Ghrelin also acts via GH-independent pathways to suppress the pro-inflammatory and catabolic milieu that drives cachexia as it stimulates the release of the anti-inflammatory cytokine IL-10 while reducing levels of TNF-α, IL-1β, and IL-6." (PMID 40869331, 2025). "The pathophysiology of cachexia is due to chronic systemic inflammation powered by pro-inflammatory cytokines such as tumour necrosis factor-alpha (TNF-a) and interleukin 6 and 1 (IL6, IL1) from tumour and host cells." (PMID 38674936, 2024). "Therefore, inhibiting IL-6 while ensuring energy intake in patients with cachexia holds promise for halting or reversing the hypermetabolic state and may be an effective treatment for cachexia." (PMID 39703501, 2024). "Furthermore, skeletal muscle IL‐6 expression was correlated with intramyocellular lipid content, suggesting that both local and systemic inflammation may contribute to ectopic fat accumulation in cachexia." (PMID 38725139, 2024). "They found that sophocarpine exerted the most potent inhibitory effect on TNF-α and IL-6 production in both RAW264.7 cells and murine primary macrophages and had a better therapeutic effect on attenuating cachexia symptoms." (PMID 38746009, 2024). "In addition, Il6ra in other cell types (such as glia cells) of the AP, or Il6ra in other brain areas (e.g., the ME, which experiences elevated IL-6 during late stages of caner progression when cachexia has started), may contribute to cachectic symptoms as well." (PMID 38824130, 2024). "NLR, PLR, SII, TNFα, IL-6, IL-8, and CRP correlated positively to cachexia and albumin while Hb and lymphocyte count correlated negatively to cachexia." (PMID 38744744, 2024).